PPARG (peroxisome proliferator activated receptor gamma)
Diseases named in the same sentence as PPARG in open-access papers (continued):
Sharing a sentence is not in itself a finding about the gene and the disease.
cancer (continued). "The unilateral effect of the PPARγ rs1801282 variant was not statistically significantly linked to the cancer risk (OR (95% CI) = 0.932 (0.830–1.046), P = 0.865), although NSAID usage unilaterally reduced this risk by a significant level (OR (95% CI) = 0.743 (0.673–0.820), P < 0.001)." (PMID 32513119, 2020). "In addition, PPARg increases plasminogen activator inhibitor expression, thus inhibiting the breakdown of the extracellular matrix and basement membrane proteins, which also reduces cancer cell invasiveness." (PMID 32850012, 2020). "Taken all together, although helix H3 mutations of PPARγ LBD found in cancers resulted in the attenuation of endogenous ligand binding due to steric hindrance, the PPARγ Q286E mutant could be potently activated regardless of ligand binding." (PMID 33266062, 2020). "However, in different types of cancer, different genes are influenced by PPARγ action." (PMID 31993929, 2020). "Therefore, we combined the effect sizes of these two strata, and the combined OR indicated that the PPARγ rs1801282 variant did not correlate with the risk of cancer at the overall level (OR (95% CI) = 0.934, (0.840–1.038))." (PMID 32513119, 2020). "In contrast to the anti-inflammatory role of PPARγ in IL-4-polarized macrophages, the enhanced PPARγ signalling in cancer-associated PMN-MDSCs decreases the lysosomal acid lipase (LAL), generating reduced ROS production and impairing cancer cell proliferation and metastasis." (PMID 32823961, 2020). "However, more recent mechanistic studies suggest that many of PPARγ's previously reported anti‐cancer properties may actually be PPARγ‐independent due to off‐target effects of its synthetic agonists." (PMID 33031638, 2020). "Furthermore, the observation of BC ADSC unresponsiveness to PPARγ canonical stimulation and inhibition could provide evidence of new deregulated and targetable cancer pathways." (PMID 31511776, 2019). "However, even though PPARγ transcript in the DEX-treated U87-MG cancer cells was significantly (P < .05) increased than that of untreated control counterpart, the expression level of transcript was observed to be detected at an extremely weak level, compared to that in A-549 and MCF-7 cancer cells." (PMID 30460096, 2018). "Therefore, lovastatin could modulate the intracellular signaling and optimize the role of troglitazone in perturbing proliferation via both the PPARγ-dependent function and a PPARγ-independent mechanism, leading to markedly efficient anti-cancer effects." (PMID 29932104, 2018). "Therefore, one might reasonably think that PPARγ could also be involved in cancer metabolism, once the receptor expression being identified in the cancer cells." (PMID 29137280, 2017). "The roles of PPARγ-mediated LPA effects in cancer are essentially unknown." (PMID 29163813, 2017). "However, function of sumoylated PPARγ in cancer lipid metabolism and cell growth regulation remains unclear." (PMID 29137280, 2017). "However, there is a conundrum for the effects of PPARγ and its ligands in cancer." (PMID 28348577, 2017). "Moreover, PPARG, the gene encoding PPARγ, is the only RXRα-heterodimerizing NR gene that exhibited recurrent genomic alterations (amplification) and high expression selectively in muscle-invasive bladder cancer (MIBC) among the cancer types profiled by TCGA." (PMID 28740126, 2017). "The vitamin D system is likewise susceptible to epigenetic regulation and, interestingly, in cancer this epigenetic repression of the vitamin D system is almost always present, which compellingly leaves the door opened to the possibility of the same phenomena happening in the PPARG system." (PMID 27579030, 2016). "Thus, PPARγ downstream signaling must play certain roles in cancer progression in our study models." (PMID 26820738, 2016). "Therefore, PPARγ may impact cancer cell proliferation through both direct and indirect mechanisms including effects on MSDCs." (PMID 26625314, 2016).
cancer (continued). "In addition to PPARα, PPARβ/δ and PPARγ were also shown to be involved in cancer." (PMID 26184238, 2015). "In addition to diabetes mellitus treatment, ligands to PPARγ could also be exploited for treating other diseases, for instance, in cancer treatment." (PMID 25866814, 2015). "In vitro and in vivo studies have demonstrated anti-proliferative and pro-apoptotic actions of PPARγ agonists such as 15-deoxy-∆-12,14-prostaglandin J2 (15dPG-J2) and thiazolidinediones (TZDs), suggesting that PPARγ could be a promising target for cancer therapy." (PMID 26184238, 2015). "However, the mechanisms by which PPARγ agonist rosiglitazone interferes with inflammation and cancer via phosphatase and tensin homolog-(PTEN)-dependent pathway remain unclear." (PMID 24757676, 2014). "Therefore, PPARγ is recognized as a therapeutically relevant target for cancer therapy." (PMID 23843889, 2013). "Although the functions of ATIP associated with microtubules are totally unknown, microtubule-targeting agents including PPARγ inhibitors such as GW9662 are a very successful class of anti-cancer drugs with therapeutic benefits in both hematopoietic and solid tumors." (PMID 23565185, 2013). "The aims are to evaluate the novel chemotherapeutic potential of PPARγ-activating drugs and provide a guide for further basic and clinical research, in order to optimize chemotherapeutic interventions that will reduce the number of cancer-related deaths worldwide." (PMID 22966225, 2012). "Although PPARγ ligands have been shown to inhibit TGFβ-stimulated profibrotic differentiation of lung fibroblasts in vitro and to reduce lung scarring in animal models of pulmonary fibrosis, the role of myofibroblast-derived PPARγ in cancer progression remains unknown." (PMID 22934105, 2012). "However, it is not the case for all neoplastic transformation, as others demonstrated that highly malignant cancer cell lines are characterized by higher expression of PPARγ and these data suggest that PPARγ may act in a cancer-permissive fashion." (PMID 22448166, 2012). "PPARγ agonists have potent PPARγ-independent effects in vitro and in vivo, regulating proinflammatory responses and acting to promote apoptosis and inhibit differentiation, which may be beneficial in treating cancer and fibrosing diseases." (PMID 22778711, 2012). "Furthermore, a better understanding of the mechanisms by which activation of PPARγ-dependent signaling stops tumourigenesis may provide the basis for future development of more efficacious drugs to prevent and/or reduce cancer-related deaths." (PMID 22966225, 2012). "Moreover, PPARγ activation induces diverse growth inhibition in different cancer cell lines." (PMID 23028383, 2012). "High-affinity synthetic ligands, the thiazolidinedione, prompted the study of PPARγ signalling pathways in the regulation of metabolic processes and are currently evaluated as possible therapeutic tools to take advantage of PPARγ prodifferentiative effects in cancer treatment." (PMID 22966223, 2012). "In addition, inhibition of Cox-2 and activation of PPARγ may have synergistic effect in inhibiting the growth of certain cancers such as pancreatic cancer." (PMID 19884989, 2009). "The metabolic and cell fate regulatory functions of PPARγ place this nuclear receptor (NR) at the cross-road of life style and diabetic comorbidity risks, which are assumed to result from the diet and/orchronic inflammation-induced sequence of preneoplastic lesions towardsmanifested cancer." (PMID 18596912, 2008). "The expressionlevels and/or the transactivation of PPARγ may be impaired in certain cancers." (PMID 18528522, 2008).
cancer (continued). "However, in recent years it has been suggested that PPARγ has a role in cancer development." (PMID 19096712, 2008). "Importantly, in several cancer cells, proline oxidase may be an important mediator of the PPARγ-stimulated generation of ROS and induction of apoptosis." (PMID 18670615, 2008). "PPARγ was initially understood as a regulator of adipocyte differentiation and glucose homeostasis while later on, it became evident that it is also involved in cell differentiation, apoptosis, and angiogenesis, biological processes which are deregulated in cancer." (PMID 18779870, 2008). "Theexact mechanisms linking modulation of PPARγ with cancer growth inhibition remain unclear." (PMID 18704200, 2008). "Interestingly, transcriptome analysis ofovarian cancer cells exposed to a PPARγ agonist revealed that PPARγ activation resulted in upregulation of severalgenes involved in protein modification and ubiquitination, including manyubiquitin ligases and ubiquitin-conjugating enzymes." (PMID 18551186, 2008). "Potential roles of targets including Akt1, PPARG, and EGFR, as well as pathways related to cancer and lipid metabolism, were further indicated by network pharmacology and molecular docking." (PMID 42198446, 2026). "Globally, CRC ranks as the third most prevalent malignancy and is responsible for approximately 10% of all mortalities attributable to cancer, and 70% of the sporadic CRC exhibits substantial PPARG regulation." (PMID 40500799, 2025). "These pathways include recruitment of CD8 T cells, recruitment of NK cells, recruitment of Tregs, cancer antigen presentation, T cell recognition of cancer cells, Cell cycle regulation, EGFR ligands, IFN-γ signature, and the PPARG network." (PMID 40895068, 2025). "Multiple factors—including MMPs, PPARγ, NF-κB, TGF-β, integrins, and various proteases—play significant roles in cancer cell proliferation, invasion, and metastasis." (PMID 40361374, 2025). "The top 200 linear model genes were screened against the known cancer driver genes in Cancer Gene Census, yielding four hits: BUB1B, EBF1, PPARG, and RECQL4." (PMID 41048341, 2025). "However, neither ERK inhibitor nor PPARγ agonist could influence CD47 expression in lamin-deficient cancer cells." (PMID 40708945, 2025). "Through its involvement in boosting fatty acid metabolism, PPARG finely tunes the activation of the PI3K/Akt/mTOR pathway, affecting both drug sensitivity and cancer cell growth." (PMID 40303293, 2025). "Although conflicting effects on cancer progression have also been described for IL18 and PPARγ, both can promote M2-like TAM differentiation, reversible by caspase-1 inhibition." (PMID 39353903, 2024). "MMPP induces cancer cells apoptosis and inhibits migration/invasion via VEGFR2/AKT and PPARγ/PTEN/AKT pathways." (PMID 37942548, 2024). "Previous studies collectively suggest that the peroxisome proliferator-activated receptor gamma (PPARG) interacts with the PTEN-PI3K/AKT signaling pathway, playing a crucial role in regulating chemosensitivity in various cancers, including HSCC." (PMID 38505269, 2024). "PPARA, PPARD and PPARG were more abnormally expressed in STAD samples and cell lines when compared to most of 32 type cancers in TCGA." (PMID 38529307, 2024). "Demonstrating a class effect of PPARγ agonists with MEK inhibitors in promoting adipogenesis is significant, as it suggests a broader therapeutic potential for this combination in cancer treatment." (PMID 39273076, 2024). "Our findings suggested that KA-induced enhancement in PPARγ activity led to ER stress and apoptosis, which subsequently led to the upregulation of NOX4 in the treated cancer cells." (PMID 39770941, 2024). "Reduced PPARG and PPARA expression have also been documented in some cancers through micro RNAs (miRNAs), long non-coding RNAs (lncRNAs), and promoter hypermethylation." (PMID 39195246, 2024).
cancer (continued). "As a partial agonist of PPARγ, the pharmacological functions of CDDO have been well studied in many disease models, such as inflammation, metabolic disorders, and cancers." (PMID 38988496, 2024). "Intriguingly, synthetic compounds known as PPARγ agonists, which activate PPARG, have shown promise as potential therapeutic agents in the treatment of cancer." (PMID 38044948, 2023). "CBD treatment upregulated apoptosis-related proteins in A549 human lung cancer cells and induced vesicle-forming components, including PPARγ and clathrin, suggesting that CBD regulates both cell death and the differentiation of cancer cells." (PMID 37837516, 2023). "Therefore, targeting PPARG may hold promise as an immunotherapy approach for BC and be associated with drug resistance and prognosis based on TME infiltration characterization of cancer tissue." (PMID 37334066, 2023). "Multiple studies have shown that peroxisome proliferator-activated receptors (PPARs, including PPARα, PPARβ and PPARγ), markers of lipid metabolism-related signalling pathways, are activated by FABP5 and are involved in the progression of human cancers." (PMID 36168624, 2022). "“Pathways in cancer” was significantly enriched in the turquoise module, containing signaling pathways such as WNT, TGF-β, PPARγ, and cytokines, whose roles have been studied in ACM." (PMID 35845067, 2022). "Although both regulate the expression of UCP-1, PPARγ, PRDM-16, PGC-1α, and other regulatory factors, the effects of nutrients, such as anti-inflammatory, anti-cancer, and anti-oxidation substances, on metabolism are more extensive." (PMID 35886989, 2022). "Our own findings on RXRα/PPARγ cytoplasmic coexpression showed that it was significantly correlated with CD133, a widely used marker for cancer stem cell (CSC)." (PMID 35406808, 2022). "The abnormal expression of targets (IL6, MAPK1, PPARG, PTGS2, and MAPK3) leads to cell proliferation and a variety of cancer types." (PMID 35992697, 2022). "And these AML cells can fully utilize fatty acid oxidation to activate cancer-promoting signaling pathways such as AMPK, and up-regulate genes such as PPARγ, FABP4, CD36 and BCL2 genes to promote their own survival and proliferation." (PMID 36002858, 2022). "On this basis, further studies will investigate in more detail PPARγ and downstream signals to better explain the positive role of different molecular forms of DHA in promoting cancer cell apoptosis." (PMID 36286423, 2022). "The analysis of the expression pattern of PPARγ and DNMT1 in different types of cancer (using TCGA) revealed that both genes are dysregulated." (PMID 34439147, 2021). "The detailed mechanism was elucidated that activating PPARγ by Alp treatment resulted in the downregulated phosphorylation of NF-κB (p65 subunit) and STAT3, two crucial regulatory pathways of cancer cachexia." (PMID 34093209, 2021). "The unique property of nuclear receptor peroxisome proliferator‐activated receptor‐γ (PPARγ; PPARG) in transmitting the anti‐survival signals of the chemotherapeutic drugs has fired the enthusiasm into the application of this receptor in cancer treatment." (PMID 34549887, 2021). "PPARγ-mediated PTEN upregulation inhibits PI3K signaling to diminish the self-renewal and aggressiveness of cancer stem cells." (PMID 33946986, 2021). "PPARγ is elevated in both ovarian and endometrial cancers and ligand activation of PPARγ increases PGRMC1 in adipocytes, making it likely that PPARγ is also involved in increasing PGRMC1 levels in reproductive cancer." (PMID 34885064, 2021). "Among multiple mode of actions, the anti-cancer activities exerted by EPA and DHA are also likely due to their ability to bind PPARγ." (PMID 32224850, 2020).
cancer (continued). "Then, 58 cancer-related targets and 66 KEGG pathways were identified, and PTGS2-, HSP90-, EGFR-, MMP2-, PPARγ-, and GSTP-mediated pathways were predicted to be the antitumor mechanisms of HD-SB." (PMID 32265701, 2020). "Thus, the activation of the PPARγ gene demonstrated to be a key regulator for adipogenesis, and the cellular differentiation into adipocytes might evidently be considered as a chemical for effective chemotherapy or alternative or combined cancer treatment." (PMID 33456717, 2020). "Interestingly, we found that helix H3 of PPARγ LBD is enriched for mutations that are found in cancers; helix H3 accounts for only 9.4% of the amino acids in the PPARγ LBD but 19.6% of PPARγ LBD mutations found in cancers (19 mutations in helix H3 among 97 mutations distributed in the PPARγ LBD)." (PMID 33266062, 2020). "In this study, we analyzed the expression signatures of PPARA, PPARD, PPARG, PPARGC1AA, and PPARGC1B in pan-cancer." (PMID 33029111, 2020). "The present results have demonstrated that activation of PPARγ using PGZ induces cellular differentiation into adipocytes and inhibits cell growth in the A549 cancer cells." (PMID 33456717, 2020). "The present study investigated the terminal differentiation capacity into adipocytes and subsequent growth inhibition in A549 cancer cells treated with pioglitazone (PGZ), a PPARγ activator." (PMID 33456717, 2020). "The cellular experiments showed that HD-SB significantly induced cancer cell apoptosis, decreased p-EGFR, HSP90 and bcl-2 expressions, and increased PPARγ, bax, cleaved caspase 3, cleaved PARP, p-AKT, and p-PI3K expressions compared with HD or SB treatment." (PMID 32265701, 2020). "The expression patterns of PPARA (p < 0.001), PPARD (p < 0.001), PPARG (p < 0.001), PPARGC1A (p < 0.001), and PPARGC1B (p < 0.001) varied in 6 immune subtypes in pan-cancers." (PMID 33029111, 2020). "Several transcription factors, including PPARγ, C/EBP, Nrf2, HOX, and HAND2, are involved in BPA action on fat and liver homeostasis, the cardiovascular system, and cancer." (PMID 32796699, 2020). "In vitro research performed on hepatic cancer cell lines pinpointed CLA as an activation ligand of PPAR-γ as well as an enhancer of PPARG expression, suggesting its impact on pro-apoptotic actions in cancer cells." (PMID 31993929, 2020). "This review focuses on the interest of using NSAIDs in cancer therapy through their capacity to regulate the aberrant canonical WNT/β-catenin pathway and PPARγ, two systems that respond in an opposite manner." (PMID 31311204, 2019). "Under normal homeostasis, PPARγ agonists directly inhibit activation of β-catenin and transcription of Wnt/β-catenin targeted genes, including COX-2, that stop cancer development and progression." (PMID 31652556, 2019). "In our study, we explored the potential of PPARG to improve radiotherapeutic efficiency against A549, NSCLC, a known radioresistant cancer cell type." (PMID 31263479, 2019). "Curcumin acts as peroxisome proliferator-activated receptor gamma (PPARγ) agonists and thus downregulate the aberrant WNT/β-catenin pathway observed in cancers." (PMID 31331376, 2019). "The administration of NSAIDs in cancer treatment would thus appear to be an interesting therapeutic strategy, which acts through their role in regulating WNT/β-catenin pathway and PPARγ activity levels." (PMID 31311204, 2019). "Thus, PPARG, PPARGC1A, and PPARGC1B might be implicated in the development of cancer." (PMID 30838172, 2019). "Similar observations have been reported when analyzing the gene regulatory profile of PPARγ and LXR receptors in cancer cells." (PMID 31437187, 2019). "Suggested molecular targets for ASX-induced cancer prevention and treatment include NF-κB, Janus kinase (JAK)/STAT-3, phosphatidylinositide 3-kinase/protein kinase B (PI3K/Akt), MAPK, Nrf2, and PPARγ." (PMID 31018521, 2019).